SIRPA (signal regulatory protein alpha)
Diseases named in the same sentence as SIRPA in open-access papers (continued):
Sharing a sentence is not in itself a finding about the gene and the disease.
cancer (continued). "Cancer cells express CD47, a "do not eat me" signal, which interacts with signal regulatory protein alpha (SIRPα) on macrophages to prevent phagocytosis." (PMID 40528159, 2025). "After treatment with conditioned medium from irradiated MC38 cells, Sirpα−/− BMDMs exhibited significant phagocytosis toward MC38 cells, whereas the same treatment did not drive WT BMDMs to phagocytize cancer cells." (PMID 34050181, 2021). "CD47-blocking antibodies have shown efficacy in preclinical cancer models and early clinical trials, but these act primarily by blocking CD47 interactions with SIRPα rather than TSP1." (PMID 33925464, 2021). "CD47 is expressed on the surface of non-malignant cells as well as multiple types of cancer cells and can bind to the SIRPα transmembrane protein on myeloid cells (especially macrophages) to form the CD47-SIRPα signaling complex." (PMID 32082311, 2020). "In addition, CD47 overexpression by cancer cells was directly related to SIRPα expression by TAMs and not with CD68+ TAMs, showing that an interplay between CD47 expressing cancer cells and the SIRPα+ Μφ exists in NSCLC." (PMID 35406573, 2022). "Thus, the effect of a clinically relevant CD47 blocking IgG4 antibody is mediated by blocking of the SIRPα/CD47 interaction and does not require expression of SLAMF7 on cancer cells." (PMID 30710089, 2019). "Furthermore, a majority of cancer cells express a high amount of CD47 at their surface, which interacts with signal regulatory protein alpha SIRPα on myeloid cells such as macrophages to transmit the “do not eat me” signal." (PMID 31547627, 2019). "Despite the fact that many cancers exploit this mechanism through increasing CD47 expression, and thereby evade attack by phagocytes, we previously found that mere depletion of the CD47-SIRPα axis or SIRPα-mediated inhibitory signaling does not lead to phagocytosis." (PMID 34050181, 2021). "We hypothesized that early-stage CIN in cancer cells can stimulate anti-cancer activity of macrophages sufficient to dominate proliferation of high CIN tumors, but probably only when maximizing pro-phagocytic conditions, such as with blockade of SIRPα (rather than ubiquitous CD47)." (PMID 38805560, 2024).
infection (56 papers, 2008 to 2026). The state of being infected such as from the introduction of a foreign agent such as serum, vaccine, antigenic substance or organism. "In vivo, Salmonella Typhimurium loads are partially increased post-infection in anti-Sirpα treated Nr2f6-deficient mice." (PMID 40605423, 2025). "SIRPα plays a critical role in the establishment of the microenvironment that induces tolerogenic training and its high expression is responsible for the increased infection of pathogenic bacteria." (PMID 36845756, 2023). "Here we show that SIRPA decreased in vitro infection by a number of pathogenic viruses, including New World and Old World arenaviruses, Zika virus, vesicular stomatitis virus and pseudoviruses bearing the Machupo virus, Ebola virus and SARS-CoV-2 glycoproteins, but not HSV-1, MLV or mNoV." (PMID 34097709, 2021). "This suggests that SIRPA is a host protein that could be targeted at the early stages of infection to inhibit infection of human pathogenic viruses." (PMID 34097709, 2021). "However, studies have shown that SIRPα mutant mice have increased susceptibility to Salmonella typhimurium infection, suggesting that SIRPα may help the host defend against infection by the pathogen." (PMID 38933265, 2024). "The increased [64Cu]Cu-SIRPα-Nb uptake in the spleen and bone marrow of all animals was more pronounced 3 and 7 wk after infection." (PMID 40876955, 2026). "[64Cu]Cu-SIRPα-Nb PET revealed an increased SUVmean in the nasal cavity in all animals after infection." (PMID 40876955, 2026). "Here we show that SIRPA, which is a major inhibitor of phagocytosis, also inhibits infection by a variety of viruses that enter via acidic compartments, including many human pathogens such as Zika, Ebola and SARS-CoV-2." (PMID 34097709, 2021). "We found that SIRPA limited infection of EBOV GP, MACV GP and VSV G pseudoviruses while knockdown of TRIM2 only affected infection by MACV and of TIM-1 by EBOV pseudotypes." (PMID 34097709, 2021). "Ex vivo infection of primary cells derived from SIRPA KO mice, which similarly lack most of the cytoplasmic domain, confirmed the phenotype observed in vitro." (PMID 34097709, 2021). "In a proof-of-concept experiment, we showed that IL-4 treatment enhanced SIRPA expression in vitro, thereby restricting virus entry and infection." (PMID 34097709, 2021). "The use of SARS-2-S pseudotypes in our experiments thus gave us an excellent system with which to test the role of entry pathway on SIRPA’s ability to inhibit infection." (PMID 34097709, 2021). "We previously identified SIRPA as a host restriction factor when testing which members of the TRIM2 interactome also diminished NWA infection." (PMID 34097709, 2021). "We also examined JUNV-C1 infection in primary fibroblasts from WT and SIRPA KO mice treated with MnCl2." (PMID 34097709, 2021). "TCRV infection levels in spleen were assayed at 7 dpi and as was seen for JUNV-C1 infections, the SIRPA KO pups showed significantly higher levels of viral RNA and titers in comparison to the WT mice." (PMID 34097709, 2021). "To further investigate the role of SIRPA’s cytoplasmic domain in infection, we made a SIRPA construct containing alanine (A) replacements for all four tyrosine residues in the ITIMs." (PMID 34097709, 2021). "In contrast, over 95% of the transgenic CD8+ T cells remaining after Cl13 infection were PD-1 high and a significant subset expressed SIRPα." (PMID 30770827, 2019). "SIRPA phosphorylation was detected in the infected brains of strains A and B but was greatly decreased in strain C or wild-type mice upon infection." (PMID 30726215, 2019). "SIRPA knockdown in the context of TRIM2 overexpression restored infection levels almost to that seen in control cells." (PMID 30726215, 2019). "We also showed that SIRPA phosphorylation is decreased upon infection; although TRIM2 also contains phosphotyrosines, infection did not lead to its dephosphorylation." (PMID 30726215, 2019).
infection (continued). "HL-60 and Huh7 cells infected with LV-SIRPα both expressed significant amount of SIRPα protein at 48 h post-infection." (PMID 27010069, 2016). "Here, we found that the delayed clearance in SIRPα mt mice only became apparent at the later stages of infection and this correlated with fewer TH17 and TH22 cells in the MLNs and colonic LP." (PMID 25236797, 2014). "Similar defects in TH17/22 generation were found during infection with C. rodentium in SIRPα mt mice, which also showed delayed clearance of the organism." (PMID 25236797, 2014). "Surprisingly, although SIRPα was undetectable in the liver of uninfected mice, the hepatic iNKT-cell response to infection was also impaired in CD47−/− mice." (PMID 19877019, 2010). "[64Cu]Cu-SIRPα-Nb uptake remained at identical levels between 3 and 10 d after infection." (PMID 40876955, 2026). "Furthermore, we confirmed specific in vivo binding of [64Cu]Cu-SIRPα-Nb by quantification of the SUVmean in both salivary gland (high SIRPα expression) and muscle (low SIRPα expression) in the PET/CT before infection." (PMID 40876955, 2026). "After infection, [64Cu]Cu-SIRPα-Nb uptake increased in 3 animals as early as 3 d after infection and decreased thereafter, whereas in the other 3 animals, [64Cu]Cu-SIRPα-Nb uptake decreased directly after infection." (PMID 40876955, 2026). "Notably, erythrophagocytosis has been previously reported to be a late consequence of LD-infection by post-translational downregulation of SIRPα on the surface of infected-MФs." (PMID 39888953, 2025). "After anti-IFNAR1 treatment, the Venus protein signal increased in several myeloid cells in the DLN, including both DC1s (CD11c+ MHC-II+ Xcr1+) and DC2s (CD11c+ MHC-II+ Sirpα+), although we cannot definitively distinguish direct infection from phagocytosis of infected cells using this assay." (PMID 39535221, 2024). "Therefore, the role of SIRPα in host defense against pathogen infection is complex and requires further exploration." (PMID 38933265, 2024). "Interestingly, SIRPA KO mice showed higher JUNV-C1 infection levels at later timepoints as well, suggesting that SIRPA contributes to diminution of viral spread in vivo." (PMID 34097709, 2021). "In addition, overexpressing SIRPα via lentivirus infection remarkably reduced microglial engulfment towards synaptosomes after Aβo treatment." (PMID 33795678, 2021). "SIRPA knockdown increased infection by SARS-2-S pseudoviruses in 293T-ACE2 cells." (PMID 34097709, 2021). "Whether SIRPA also restricts infection in these cell types and limits SARS-CoV-2 infection in vivo remains to be tested." (PMID 34097709, 2021). "We suggest that SIRPA restricts virus internalization an early step in infection by limiting integrin activation, which similar to phagocytosis may be required to allow virus engulfment." (PMID 34097709, 2021). "Indeed, SIRPA only restricted infection of 293T-ACE2 cells, in which trafficking to the cathepsin-containing acidic endosomes is required for entry, but not of Calu-3 lung epithelial cells, which express both ACE2 and TMPRSS2 on the surface." (PMID 34097709, 2021). "Thus, SIRPA controls both in vitro and in vivo infection by viruses using the acidic endosomal pathway for entry." (PMID 34097709, 2021). "The Ad-shSIRPα infection at MOI 10.0 greatly reduced SIRPα expression relative to Ad-shControl." (PMID 32411788, 2020). "Again, only TRIM2 and SIRPA depletion resulted in increased infection." (PMID 30726215, 2019). "Whether infection leads to SIRPA dephosphorylation and disassociation from TRIM2 or follows the dissociation is currently under investigation." (PMID 30726215, 2019). "We identified Sirpα as a gene of interest because it showed an expression pattern similar to PD-1 over time and had sustained upregulation during Cl13 chronic infection compared to more transient expression with Arm infection." (PMID 30770827, 2019). "Over 90% of the transgenic CD8+ T cells remaining after Arm infection were PD-1 low and SIRPα−." (PMID 30770827, 2019).
infection (continued). "In conclusion, our findings uncover the molecular mechanism by which nicotine attenuates the phagocytic ability of macrophages by regulating the c-Myc-miR-296-3p–SIRPα signal and suggest that the signal may be a potential therapeutic target against pathogen infection." (PMID 36845756, 2023). "We overexpressed a FLAG-tagged expression construct encoding human SIRPA (WT) and a mutant construct lacking most of the cytoplasmic domain (ΔCyto) and tested their effect on infection with replication-competent viruses and pseudoviruses in U2OS and 293T-ACE2 cells, respectively." (PMID 34097709, 2021). "Next, we tested whether infection with Candid 1 altered phosphorylation of TRIM2 or SIRPA." (PMID 30726215, 2019). "Thus, during both acute and chronic FV infections, the expression of SIRPα correlated with enhanced cytolytic ability and proliferative capacity, suggesting that SIRPα identified cells that sustained an antiviral response during chronic infection." (PMID 30770827, 2019). "Furthermore, the sustained expression of Sirpα on CD8+ T cells late after infection with Cl13 suggested that it might identify an interesting subset of cells during exhaustion." (PMID 30770827, 2019). "We then infected Calu-3 and 293T-ACE2 cells with SARS-2-S and control VSV-G pseudoviruses after knockdown of SIRPA and ACE2 and measured infection by luciferase assays." (PMID 34097709, 2021). "We also performed JUNV-C1, LCMV and VSV VIAs with SIRPA KO and WT BMDMs; cells from TRIM2 KO mice served as a control for the arenavirus infections." (PMID 34097709, 2021). "Newborn SIRPA KO and WT mice were also infected with MLV, and infection was analyzed at 16 dpi by measuring virus titers in spleen, a technique commonly used in the field." (PMID 34097709, 2021). "SIRPA overexpression in U2OS cells blocked Candid 1 infection to a similar extent, as TRIM2 overexpression and SIRPA knockdown also increased infection by Parodi-GP pseudotyped MLV." (PMID 30726215, 2019). "However, SHP-2 is involved in many pathways, so the inhibition of infection found in cells depleted for SHP-2 may not be directly linked to its interaction with SIRPA." (PMID 30726215, 2019). "MnCl2 treatment increased infection in WT cells, but did not further enhance infection in SIRPA KO fibroblasts." (PMID 34097709, 2021). "Moreover, we show that a member of the TRIM2 interactome, signal regulatory protein α (SIRPA), which is well-known for inhibiting phagocytosis by macrophages, interacts with TRIM2 and also blocks NWA infection." (PMID 30726215, 2019). "Moreover, when we coimmunoprecipitated TRIM2 and SIRPA, we found that the interaction between TRIM2 and SIRPA decreased upon infection." (PMID 30726215, 2019). "Our previous data on SIRPα-CD47 have suggested that cognate receptor–ligand interactions also regulate NKT cell retention on infected KCs, with the induced expression of SIRPα after infection being preferentially, but not exclusively observed on infected KCs." (PMID 29636754, 2018). "Over-expression of SIRPA WT reduced infection by JUNV-C1, LCMV and VSV viruses and pseudoviruses bearing viral glycoproteins from MACV and SARS-CoV-2, while infection levels in ΔCyto-expressing cells were similar to those observed for the pcDNA empty vector control." (PMID 34097709, 2021). "Taken together, these data suggest that phosphorylated SIRPA binds to TRIM2 and that this complex blocks virus internalization; dephosphorylation of SIRPA, either directly by SHP-2 or by other cellular phosphatases activated by infection, leads to dissociation of the complex and allows infection." (PMID 30726215, 2019). "However, knockdown of SIRPA in strain A or B mice did not further increase infection, nor was SIRPA surface expression diminished in the TRIM2 knockout mice." (PMID 30726215, 2019).
infection (continued). "The [64Cu]Cu-SIRPα-Nb biomarker investigated here represents a possibility for PET imaging of myeloid cells, which may contribute to better understanding of the pathophysiology of infection, the hyperinflammatory response in the active phase of the infection, and long-term inflammatory processes." (PMID 40876955, 2026). "We found that depletion of SIRPA increased infection by JUNV-C1, TCRV, LCMV, VSV and ZIKV, but did not affect infection by mNoV, MLV or HSV-1." (PMID 34097709, 2021). "SIRPA and TRIM2 also colocalized in transfected U2OS cells; this colocalization was not affected by NWA infection." (PMID 30726215, 2019). "However, SIRPA knockdown did not significantly increase SARS-2-S pseudovirus infection in Calu-3 cells, while ACE2 knockdown greatly decreased infection in both cell types." (PMID 34097709, 2021).
hematological malignancies (25 papers, 2017 to 2025). "More studies are also required to evaluate the effect of CD47/SIRPα-targeted ADCs on hematological malignancies." (PMID 35978372, 2022). "Based on this research, CD47/SIRPα-targeted BsAbs are potential treatment options for hematological malignancies." (PMID 35978372, 2022). "Significant progress has been made in research in Bispecific T cell engagers (BiTE) and anti-CD47/SIRPα antibodies in the treatment of hematological malignancies." (PMID 35978372, 2022). "Further studies are required to investigate the efficacies of CD70/SIRPα BsAb in CD70hi hematological malignancies." (PMID 35978372, 2022). "This class of therapeutics constitute the majority of the available in-human data testing CD47/SIRPα inhibition in solid tumors and hematologic malignancies, although data remains limited." (PMID 34944850, 2021). "Specifically, granulocytes with SIRPA-expression are more abundant in CRC stroma than those observed in hematological malignancies." (PMID 33799989, 2021). "CD47/SIRPα-based therapies have been proven as an effective treatment for solid tumors and hematologic malignancies, with several clinical trials including CD47-blocking monoclonal antibodies or SIRPα-Fc fusion protein." (PMID 31829270, 2019). "Many solid and hematologic malignancies express CD47 on their cell surface to display an anti-phagocytic signal to SIRPα-expressing myeloid cells and evade destruction by innate and adaptive immune system." (PMID 28077173, 2017). "Notably, SIRPA-targeting drugs such as evorpacept and maplirpacept have been investigated in clinical trials for hematological malignancies." (PMID 40299563, 2025). "Hence, blockade of CD47/SIRPα signaling was regarded to increase phagocytosis by TAMs in solid tumors and hematological malignancies." (PMID 40050933, 2025). "More CD47/SIRPα-targeted BsAbs for hematological malignancies are on the way." (PMID 35978372, 2022). "In hematological malignancies, those that block the CD47/SIRPα axis and PD-1/PD-L1 axis have demonstrated promising clinical responses." (PMID 35978372, 2022). "CD47 binding to SIRPα has been well studied because SIRPα is a phagocytosis checkpoint, and its modulation has significant clinical applications, such as for the treatment of patients with AML and other hematologic malignancies." (PMID 34944878, 2021). "As a dual-functioning soluble decoy receptor with the CD47-binding domain of SIRPα fused to an IgG1 Fc region, TTI-621 had been applied intravenously for hematological malignancies and intratumorally for solid tumors and mycosis fungoides." (PMID 34717705, 2021). "Clinical trials have been initiated to investigate the effects of combining Azacitidine (Aza), an anti-metabolite chemotherapy drug, with CD47/SIRPα inhibition, such as the anti-CD47 monoclonal antibody (mAb) Magrolimab, in patients with hematologic malignancies." (PMID 39040441, 2024). "Clinical trials have confirmed that the potency and efficacy of CD47/SIRPα-based therapy, utilizing CD47-blocking monoclonal antibodies (Abs) or SIRPα-fragment crystallizable (Fc) fusion proteins, is a potent and efficacious approach for treating both solid tumors and hematologic malignancies." (PMID 38398223, 2024).
hematologic cancers (6 papers, 2021 to 2023). "Ongoing clinical studies have been conducted to inhibit the CD47–SIRPα axis using several antibodies or fusion proteins targeting CD47 and SIRPα in some solid and hematologic cancers." (PMID 37894750, 2023). "Anti-CD47 mAbs and selective SIRPα blockers had similar efficacy in hematologic cancers, with ORRs of 29.8% and 23.0%, respectively (p=0.48, DCR p=0.69)." (PMID 36439116, 2022). "Collectively, preliminary results of clinical trials with CC-95251 and BI765063 have suggested the limited toxicity of targeting SIRPα in patients with solid or hematologic cancers." (PMID 35884427, 2022). "In our analysis, greater response was seen in hematologic cancers, with similar rates for both anti-CD47 mAbs and selective SIRPα blockers." (PMID 36439116, 2022).
neurodegenerative disease (6 papers, 2014 to 2024). A disorder of the central nervous system characterized by gradual and progressive loss of neural tissue and neurologic function. "It is expressed in most mammalian cells, including neurons, and inhibits phagocytosis in neurodegenerative diseases through signal-regulatory protein alpha (SIRP α) on microglia." (PMID 35959472, 2022). "The characteristics of CD11c+ microglia in our mutant mice were similar to those of the ‘primed microglia’ that have been observed in aging and neurodegenerative diseases; thus, SIRPα is a possible key component of the regulation of microglia priming in vivo." (PMID 30910011, 2019). "We focus here on how SIRPα inhibits the phagocytosis of the tissue debris “degenerated myelin” which hinders repair in axonal injury and neurodegenerative diseases." (PMID 24795566, 2014).